ABHD5 (abhydrolase domain containing 5, lysophosphatidic acid acyltransferase)
Diseases named in the same sentence as ABHD5 in open-access papers (continued):
Sharing a sentence is not in itself a finding about the gene and the disease.
cancer (26 papers, 2016 to 2026). A tumor composed of atypical neoplastic, often pleomorphic cells that invade other tissues. "Collectively, our results not only revealed the mechanisms underlying the inhibition of cell proliferation by ABHD5 but also underscore the possibility of targeting cancer by activation of lipolysis." (PMID 33219129, 2021). "Further studies showed that the exacerbation of NLRP3 inflammasome activation by ABHD5 deficiency, provides a positive feedback loop to promote cancer progression by preferentially secrete the proinflammatory cytokine IL-1β." (PMID 32867817, 2020). "In the present study, we further revealed that the exacerbation of NLRP3 inflammasome activation by ABHD5 deficiency, provides a positive feedback loop to promote cancer progression by preferentially secrete the proinflammatory cytokine IL-1β." (PMID 32867817, 2020). "Another interesting phenomenon was that the expression of ABHD5 in CRC cells or cancer-associated macrophages was opposite." (PMID 27189574, 2016). "This review brings together experimental and clinical evidence to map the diverse, sometimes contradictory roles of ABHD5 in cancer." (PMID 41749838, 2026). "In contrast, deletion of PNPLA2 did not affect proliferation and colony formation, further supporting a unique role for ABHD5 in suppressing cancer cell aggressiveness." (PMID 41349769, 2025). "Investigations conducted in vitro, in xenograft models, and in genetic cancer models have demonstrated that ABHD5 expression in macrophages suppresses the migration of cancer cells." (PMID 39328203, 2024). "Overall, this study indicates that ABHD5 in macrophages inhibits the production of MMPs and cancer metastasis, making ABHD5 a prognostic marker for CRC." (PMID 39328203, 2024). "There are considerable differences among various malignant tumors, such as differences in the microenvironment, metabolic demands, interactions among different signaling pathways, and cellular responses to ABHD5." (PMID 39328203, 2024). "Our work provides fundamental insight into the structure of ABHD5 and its ligand-binding mode, which can be further applied to develop ABHD5 as a therapeutic target for metabolic disease and cancer." (PMID 35836935, 2022). "Collectively, activation of ABHD5-mediated lipolysis, genetically or pharmacologically, impedes mTORC1 signaling and inhibits the anabolism of cancer cells." (PMID 33219129, 2021). "Using SR-3420, a highly selective synthetic agonist for ABHD5-mediated lipolysis, we demonstrated that pharmacological activation of ABHD5 potently inhibits mTORC1, the master signaling driver for cancer cell anabolism." (PMID 33219129, 2021). "To investigate the molecular basis by which ABHD5 inhibits the proliferation of cancer cells, we profiled the transcriptomes of 22Rv1-ABHD5 cells grown in the presence and absence of Dox." (PMID 33219129, 2021). "We demonstrated that loss of ABHD5 retain YAP in the nucleus via promoting SET1A methylation of YAP, further explaining how YAP methylation and activation are triggered in cancer cells." (PMID 34795238, 2021). "Since ABHD5 can be targeted by small ligands, these results pave an avenue toward developing new cancer therapeutics through pharmacological activation of ABHD5-mediated lipolysis." (PMID 33219129, 2021). "In this regard, mining the data of cancer patient survival revealed that high ABHD5 expression is associated with significantly better prognosis in four different cancer types, suggesting that ABHD5 activation might be developed into an effective therapy in a broad spectrum of cancer diseases." (PMID 33219129, 2021). "Collectively, these experiments identified a novel regulatory cascade through which activation of ABHD5 inhibits cancer anabolism by creating a futile cycle of TG hydrolysis and synthesis that activates AMPK and subsequently inhibits mTORC1." (PMID 33219129, 2021).
cancer (continued). "Overall, reduced ATGL activity, via knockdown of ATGL or ABHD5, has similar effects on cancer cell proliferation and viability as increased ATGL activity, via overexpression of ATGL or knockdown of HILPDA." (PMID 33413672, 2021). "A similar phenomenon was also observed in our previous study regarding the expression of ABHD5 in cancer cells and TAMs2." (PMID 29968710, 2018). "Deficiency of CGI-58, the coactivator of ATGL encoded by ABHD5, results in increased tumorigenesis and malignant transformation in mice and ABHD5 deletions occur in several human cancers." (PMID 28459858, 2017). "Blocking of DGAT1 leads to blockage of storage while blockage of ABHD5 leads to blockage of usage; hence both the siRNA treatments lead to unavailability of FA for cancer cell proliferation and decreased growth." (PMID 28877685, 2017). "ABHD5 has been investigated in various research for its role in various forms of cancer." (PMID 39093497, 2024). "The expression of ABHD5 and related signaling in some cancers." (PMID 39328203, 2024). "This review summarizes the role of ABHD5 in various malignant tumors and explores the different signaling pathways and metabolic routes that may be involved, providing a comprehensive mechanistic understanding of ABHD5." (PMID 39328203, 2024). "Recent data demonstrates that ABHD5 is the target of synthetic and endogenous ligands that might be therapeutic beneficial for treating metabolic diseases and cancers." (PMID 35173175, 2022). "To address this possibility, we examined whether ABHD5 gene expression levels correlated with cancer patient survival data in the publicly accessible database, the Kaplan–Meier Plotter." (PMID 33219129, 2021). "Collectively, this study maps out a novel molecular pathway crucial for limiting cancer cell proliferation, in which ABHD5-mediated lipolysis creates an energy-consuming futile cycle between TG hydrolysis and resynthesis, leading to inhibition of mTORC1 and cancer cell growth arrest." (PMID 33219129, 2021). "Although ABHD5 is an essential activator for TG lipase ATGL, it was unclear whether the cancer suppression by ABHD5 involves lipolytic activity and, if so, the signaling pathways involved." (PMID 33219129, 2021). "Our study identified ABHD5 as an upstream factor that regulates DPY30 degradation and nuclear translocation, suggesting the mechanism underlying DPY30 overexpression and activation in cancer pathogenesis." (PMID 34795238, 2021). "Notably, our series of studies gradually revealed the PNPLA2-independent roles of ABHD5 in the cancer field." (PMID 34795238, 2021). "Collectively, these results indicate that ABHD5 protects against patient death in multiple cancer types and that activation of ABHD5 may represent a promising therapeutic opportunity against these cancers." (PMID 33219129, 2021). "As such, the influence of ABHD5 on cancer cell biology, affecting fatty acid mobilization, maybe through ATGL-dependent and independent mechanisms, but the impact on oncogenesis remains to be defined." (PMID 33413672, 2021). "Therefore, our results suggest that an energy-consuming futile cycle of FA generation and esterification is responsible for AMP accumulation and AMPK activation downstream of ABHD5 activation in cancer cells." (PMID 33219129, 2021). "Since both DGAT1 and ABHD5 are overexpressed in cancer cells and CTCs vigorously uptake lipid as compared to PBMCs, targeting them may represent a new oncolytic approach." (PMID 28877685, 2017). "By contrast, in the cancer cells with impaired autophagic flux, such as ABHD5 deficient cancer cells, FU treatment could not induce neither the prosurvival autophagy nor autophagic degradation of RNA." (PMID 30842415, 2019). "Knocking down ABHD5 in LNCaP cells promotes epithelial−mesenchymal transition (EMT), enhancing cancer cell mobility and invasiveness." (PMID 39328203, 2024).
cancer (continued). "A previous study showed that ABHD5 activated the AMPK signaling pathway to suppress the mTOR signaling pathway, leading to the suppression of cancer cell anabolism." (PMID 39093497, 2024). "Mechanistically, TRIM59 promoted abhydrolase domain containing 5 (ABHD5) degradation and activation of NLRP3 inflammasome in macrophages, which in turn released proinflammatory cytokines, thus sustaining cancer cell proliferation and invasion." (PMID 35814425, 2022). "To further evaluate the effects of ABHD5 knockdown on CRC stemness, we performed limiting dilution analysis, the gold standard in vivo assay for determining the stemness capacity of cancer cells." (PMID 34795238, 2021). "In addition, we observed that cancer-associated T cells overexpressed ABHD5 (data not shown)." (PMID 27189574, 2016). "This suppressive effect of macrophage ABHD5 on cancer cell migration is independent of its metabolic functions, as neither triglycerides nor metabolites regulated by ABHD5 impact cancer cell migration." (PMID 39328203, 2024). "Further studies focused on the effect of the classic lipolytic factor, ABHD5, on epigenetic modification of histone/non-histone proteins, and its relevance to cancer pathogenesis should be derived from this study." (PMID 34795238, 2021). "Surprisingly, knockdown of ATGL, the primary target of ABHD5, inhibited cell proliferation and migration, raising a critical question of whether ABHD5 and ATGL can functionally interact to regulate cancer cell metabolism." (PMID 33219129, 2021). "While it is clear that activation of the ABHD5/ATGL pathway suppresses cancer cell growth, the mechanisms involved are not fully understood." (PMID 33219129, 2021). "Interestingly, in contrast to ABHD5 levels, macrophage SRM expression and spermidine levels were decreased in human carcinoma tissues compared with adjacent normal tissues." (PMID 27189574, 2016). "Thus, targeting metabolic regulators like ABHD5 that converge on oncogenic nodes such as c-MYC may provide a novel therapeutic avenue for prostate and other MYC-driven cancers." (PMID 41349769, 2025). "Furthermore, the level of ABHD5 expression in human CRC tissues is inversely correlated with the degree of CRC malignancy, suggesting that ABHD5 may influence the malignant transformation of cancer by regulating metabolic effects such as the Warburg effect." (PMID 39328203, 2024). "Interestingly, a recent study showed that cancer cell TG hydrolase activity in vitro is not activated by ABHD5, while others have reported that ABHD5 possesses lysophosphatidate acyl transferase (LPAAT) activity, converting lysophosphatidate into phosphatidate." (PMID 33413672, 2021).
genetic disorder (5 papers, 2014 to 2026). "Because of its association with a human genetic disease and its interesting dual role in lipid droplet and lipoprotein metabolism, we focused here on ABHD5." (PMID 27124600, 2016).
ABHD5 also shares sentences with these, for which no sentence is quoted: Insulin resistance (5 papers); metabolic disease (4); autosomal recessive congenital ichthyosis (3); Cachexia (3); hepatoma (3); myopathy (3); Glucose intolerance (2); atherosclerosis (1); breast carcinoma (1); bullous congenital ichthyosiform erythroderma (1); cardiac hypertrophy (1); cardiomyopathy (1); cardiovascular diseases (1); chronic hepatitis C (1); congenital ichthyosiform erythroderma (1); congenital ichthyosis (1); coronary artery disease (1); diabetes (1); gastric cancer (1); gestational diabetes (1); hearing loss (1); Hepatic fibrosis (1); hereditary spastic paraplegia (1); hyperlipidemia (1); ichthyosiform erythroderma (1); myocardial infarction (1); nonalcoholic fatty liver (1); ovarian carcinoma (1); overnutrition (1); polyneuropathy (1).
A further 6 diseases each share a sentence with ABHD5 in 1 paper.